DPP4 (dipeptidyl peptidase 4)
Diseases named in the same sentence as DPP4 in open-access papers (continued):
Sharing a sentence is not in itself a finding about the gene and the disease.
angioedema (24 papers, 2008 to 2025). Swelling involving the deep dermis, subcutaneous, or submucosal tissues, representing localized edema. "Dipeptidyl peptidase-4 (DPP-4) plays a minor role in degrading vasoactive peptides that cause angioedema when angiotensin-converting enzyme (ACE) is present and fully functional." (PMID 35907939, 2022). "Evidence from previous studies implicates DPP-4 deficiency in the pathogenesis of vasoactive peptide-induced angioedema." (PMID 34884209, 2021). "Longitudinal observational research is needed to fully understand the association between ACE inhibitor/DPP-4 inhibitor use and vasoactive peptide-induced angioedema." (PMID 34884209, 2021). "This review explores management strategies such as fresh frozen plasma, icatibant, ecallantide, and C1 inhibitor concentrate, and considers alternative drug options like angiotensin II receptor blockers and potential associations of DPP-4 inhibitors with ACE inhibitor-induced angioedema." (PMID 38543146, 2024). "DPP-4 inhibitors can extend the half-lives of bradykinin and substance P, therefore increasing the risk of hypersensitivity reactions, especially angioedema; which is among the hypersensitivity reactions reported in the prescribing information of most DPP-4 inhibitors as post-marketing events." (PMID 38523307, 2024). "Reduced DPP-4 enzyme activity and DPP-4 enzyme deficiency have been associated with an increase in ACE inhibitor-induced angioedema in rats and humans, and it was hypothesized that concomitant use of DPP-4 inhibitors and ACE inhibitors could increase the risk of angioedema-related adverse events." (PMID 20412573, 2010). "DPP-4 inhibitors can increase levels of bradykinin by inhibiting its breakdown, leading to increased levels of bradykinin and subsequent angioedema." (PMID 38957198, 2023). "This study investigated the association between DPP-4 inhibitors (DPP-4Is) and angioedema, including cases where the concomitant use of ACE inhibitors (ACEIs) was absent." (PMID 35907939, 2022). "Of the patients treated with DPP-4 inhibitors, four developed drug-induced angioedema in combination with ACE inhibitors, and all were taking vildagliptin." (PMID 34884209, 2021). "Of the reported cases of DPP-4 inhibitor-induced angioedema, four were in combination with an ACE inhibitor." (PMID 34884209, 2021). "This study found that ACE inhibitors and DPP-4 inhibitors, which inhibit the degradation of substance P and bradykinin, tended to have different effects on the onset of angioedema in clinical practice." (PMID 34884209, 2021). "In fact, clinical case reports have described the development of angioedema in some patients receiving CD26/DPP4 inhibitors (anagliptin and sitagliptin)." (PMID 34944016, 2021). "It has also been reported that some individuals who experience vasoactive peptide-induced angioedema have lower serum DPP-4 enzyme activity than control subjects." (PMID 34884209, 2021). "In this study, we found that ACE inhibitors and DPP-4 inhibitors that inhibit the degradation of substance P and bradykinin tend to have different effects on the onset of angioedema in clinical practice." (PMID 34884209, 2021). "Contraindications for treatment with a DPP-4 inhibitor include serious hypersensitivity (e.g., anaphylaxis, angioedema) to a specific DPP-4 inhibitor or any component of the formulation." (PMID 32308645, 2020). "Researchers have suggested that reduced DPP-4 enzyme activity and DPP-4 enzyme deficiency increase ACE inhibitor-induced angioedema in rats and potentially humans." (PMID 18954434, 2008). "The exploration of alternative drug options such as angiotensin II receptor blockers, the potential association of coadministration of DPP-4 inhibitors with ACE inhibitors, the presentation of angioedema and the significant clinical importance of this condition are also discussed." (PMID 38543146, 2024).
angioedema (continued). "However, the angioedema episodes described herein occurred in a reduced kinin catabolism condition, similarly to iatrogenic angioedema with ACEi and dipeptidyl-peptidase 4 inhibitors." (PMID 38445235, 2024). "Drugs, particularly angiotensin-converting enzyme inhibitors (ACEi) and less frequently angiotensin II receptor antagonists (ARA-II), dipeptidyl peptidase 4 (DPP-IV) inhibitors and sacubitril, involved in kinin degradation, have been associated with bradykinin-mediated angioedema." (PMID 36238930, 2022). "This study suggests that the use of ACE inhibitors and DPP-4 inhibitors, which inhibit the degradation of substance P and bradykinin, in the clinic tend to have different effects on the onset of vasoactive peptide-induced angioedema." (PMID 34884209, 2021). "On the other hand, spontaneous reports (including post-marketing reports) have been reported but, so far, epidemiological studies have not demonstrated an increased risk of DPP-4 inhibitors in a lone induced angioedema." (PMID 34884209, 2021). "This suggests that vasoactive peptide-induced angioedema may result from impaired substance P degradation by DPP-4 inhibitors." (PMID 34884209, 2021). "Vasoactive peptide-induced angioedema may onset not only in ACE inhibitors but also in DPP-4 inhibitors." (PMID 34884209, 2021). "Thus, DPP-4 inhibitor-induced angioedema should be carefully considered and monitored, especially during concurrent treatment with ACE inhibitors." (PMID 34884209, 2021). "One hundred and one cases of angioedema associated with DPP-4 inhibitors were reported, and no signal was detected." (PMID 34884209, 2021). "These authors hypothesized that the concomitant use of DPP-4 inhibitors and ACE inhibitors could increase the risk of angioedema-related adverse experiences." (PMID 18954434, 2008). "Our study supported the hypothesis that DPP4-Is may induce angioedema in susceptible patients, even in the absence of concomitant ACEI." (PMID 35907939, 2022). "Therefore, vasoactive peptide-induced angioedema may onset not only in ACE inhibitors but also in DPP-4 inhibitors." (PMID 34884209, 2021). "However, the contribution of impaired degradation of substance P by DPP-4 to the pathogenesis of vasoactive peptide-induced angioedema is unknown." (PMID 34884209, 2021). "It is also important to avoid angioedema triggers in HAE-nC1-INH, such as estrogen-containing oral contraceptives or estrogen replacement therapy, dipeptidyl peptidase-4 (DPP-4) inhibitors, neprilysin inhibitors and ACE inhibitors." (PMID 39654054, 2024). "Furthermore, signals of angioedema with the combination of ACE and DPP-4 inhibitors have been reported in research using the WHO pharmacovigilance database." (PMID 34884209, 2021). "No angioedema signals were detected for DPP-4 inhibitors; however, a signal was detected for ACE inhibitors (IC: 2.42, 95% confidence interval (CI): 2.19 to 2.65)." (PMID 34884209, 2021). "In this study, we sought to clarify whether dipeptidyl peptidase-4 (DPP-4) and angiotensin-converting enzyme (ACE) inhibitors that suppress the degradation of substance P and bradykinin are involved in angioedema onset." (PMID 34884209, 2021). "However, no signal of angioedema was detected with the DPP-4 inhibitors, in contrast to some ACE inhibitors." (PMID 34884209, 2021).
acute pancreatitis (23 papers, 2010 to 2025). An acute inflammatory process that leads to necrosis of the pancreatic parenchyma. "Acute pancreatitis, a rare but severe side effect of DPP4 inhibitors, was associated with increased activity of GLP-1, which can cause ductal hyperplasia in the pancreas with outflow obstruction leading to intrapancreatic activation of pancreatic enzymes." (PMID 39861115, 2025). "Results from the Cox proportional hazard model (HR) analysis, the DPP-4 inhibitor was associated with a neutral risk of acute pancreatitis HR 0.68; 95% CI: 0.42–1.09." (PMID 39027329, 2024). "Several retrospective studies and meta-analyses on the association of DPP-4 inhibitor therapy and pancreatitis have altogether shown a low risk for acute pancreatitis." (PMID 31275246, 2019). "Before this review, three other meta-analyses evaluated the association between clinical use of DPP-4 inhibitors and acute pancreatitis." (PMID 29335646, 2018). "DPP-4 inhibitors were associated with increased risk for acute pancreatitis (Peto odds ratio 1.72; 95% CI 1.18–2.53), with an NNH of 1066 patients, but the optimal sample size for this outcome was not reached." (PMID 29335646, 2018). "DPP-4 inhibitors were associated with an increased risk of acute pancreatitis in direct meta-analysis (Peto odds ratio 1.72; 95% CI 1.18–2.53) and with an absolute risk difference of 0.1% (representing a number needed to harm (NNH) of 1066)." (PMID 29335646, 2018). "Concerns over an increased risk of acute pancreatitis with the DPP4 inhibitors and GLP-1 receptor agonists have been raised based on case reports." (PMID 30310100, 2018). "The other two1,3 found an increased risk of acute pancreatitis in patients treated with DPP-4 inhibitors; however, they included only three large cardiovascular randomised trials, namely, EXAMINE, SAVOR-TIMI 53 and TECOS18–20." (PMID 29335646, 2018). "Since most clinical trials and observational studies either excluded or did not include sufficient number of type 2 patients at high risk of acute pancreatitis, the safety of DPP-4 inhibitors in this subgroup of patients deserves further studies." (PMID 26886601, 2016). "In summary, based on this extensive nationwide cohort study in Taiwan with a significant number of incident cases, the use of DPP-4 inhibitors appears to be unrelated to an increased risk of recurrent acute pancreatitis, in those who have a prior history of acute pancreatitis in stable condition." (PMID 39027329, 2024). "Thus, the safety of DPP-4 inhibitors, or any medication, in specific subgroups of patients, such as those at high risk of acute pancreatitis, should be a subject of further study." (PMID 39027329, 2024). "Indeed, the literature on the association between drugs like DPP-4 inhibitors and acute pancreatitis can be complex and sometimes contradictory." (PMID 39027329, 2024). "An increased risk was also supported by results of a large meta-analysis comprising a total of 36 double-blind randomized clinical trials with DPP-4 inhibitors with a total of 54,664 patients: there was a 58% increased risk of acute pancreatitis with DPP-4 inhibitors compared with other therapies." (PMID 31275243, 2019). "As we aimed to be conservative, TSA was performed to assess whether there was enough information to reach a definite conclusion regarding the association between DPP-4 inhibitors and acute pancreatitis." (PMID 29335646, 2018). "We present the case of a 57-year-old male who developed DPP-4 inhibitor-induced acute pancreatitis after the initiation of linagliptin." (PMID 33927920, 2021). "Within the acute pancreatitis cohort, there were 8,419 initiators of a DPP4 inhibitor and 28,858 initiators of a sulfonylureas." (PMID 30310100, 2018). "Several previous observational studies have examined the relationship between DPP4 inhibitors and acute pancreatitis." (PMID 30310100, 2018). "There were 64 events of acute pancreatitis in the DPP-4 inhibitor group and 39 events in the control group." (PMID 29335646, 2018).
acute pancreatitis (continued). "After 31,520 years of person-time follow-up this cohort experienced 41 episodes of acute pancreatitis among new users of DPP4 inhibitors (n = 7, incidence rate = 0.9 per 1000 person-years) and sulfonylureas (n = 34, incidence rate 1.4 per 1000 person-years)." (PMID 30310100, 2018). "We found no significant increased risk of recurrent acute pancreatitis associated with DPP-4 inhibitors." (PMID 39027329, 2024). "In this large nationwide retrospective cohort study, we analyzed the risks of hospitalization for acute pancreatitis associated with DPP-4 inhibitors compared with non-DPP-4 inhibitors in patients with T2D with a prior history of acute pancreatitis." (PMID 39027329, 2024). "Presently, it stands as the largest observational study investigating the potential link between DPP-4 inhibitors and acute pancreatitis, uniquely concentrating on individuals with T2D, particularly those with a history of prior hospitalization for acute pancreatitis." (PMID 39027329, 2024). "Our findings add to this evidence base suggesting that DPP4 inhibitors do not substantially increase the risk of acute pancreatitis compared to other glucose-lowering agents." (PMID 30310100, 2018). "Currently, this is the largest observational study looking for the association of DPP-4 inhibitors on acute pancreatitis in non-Caucasian population." (PMID 26886601, 2016). "Therefore, current results from RCT are insufficiently powered to clarify the effect of DPP-4 inhibitor on acute pancreatitis." (PMID 26886601, 2016). "Large-scale Japanese studies including our analysis on nationwide claims database have not demonstrated a causal link between DPP-4 inhibitors and acute pancreatitis, possibly due to differences in genetic predisposition, dietary habits, and lower baseline pancreatic fat accumulation." (PMID 40607140, 2025). "Although a few potential risks associated with DPP-4 inhibitors have been reported with respect to effects in the immune system and risk of acute pancreatitis, there is a relative lack of unwanted off-target or adverse effects associated with the DPP-4 inhibitors that are used therapeutically." (PMID 33923115, 2021). "There seemed to be an association between the use of DPP-4 inhibitors and acute pancreatitis, although the number of randomised patients was not sufficient for a firm conclusion and the estimated risk of acute pancreatitis is small (one patient in 1066 patients treated with DPP-4 inhibitors)." (PMID 29335646, 2018). "Furthermore, a retrospective cohort study of Japanese diabetic patients suggested that treatment with DPP-4 inhibitors does not increase the risk of acute pancreatitis." (PMID 26137940, 2015).
ovarian carcinoma (23 papers, 2013 to 2025). A malignant neoplasm originating from the surface ovarian epithelium. "Loss of DPP4 contributes to tumorigenesis in several cancers, including ovarian carcinoma, whereas forced expression has shown growth inhibitory effect on glioma cells." (PMID 28893231, 2017). "In ovarian carcinoma and mesothelioma, increase DPP4 expression can also improve cancer cells susceptibility to chemotherapy." (PMID 27936466, 2017). "DPP4 expression has been associated with tumour initiating cell populations in several tumour types, and ovarian cancer spheroids (free-floating organoids with a hypoxic core) found in ascites fluid contain putative ovarian cancer stem cells." (PMID 33143089, 2020). "DPP4 is reported as a positive prognostic factor in ovarian cancer and an established marker for diagnosis in cutaneous T cell lymphoma." (PMID 35158891, 2022). "DPP4 contributes to ferroptosis in clear cell renal cell carcinoma, while DPP4 had high mRNA expression under hypoxic growth in ovarian cancer cells." (PMID 34359286, 2021). "From a therapeutic perspective, our results provide a strategy to improve immune responses in ovarian cancer and establish a rationale for the use of DPP4 inhibitors as a rapidly translatable second-line treatment for this disease." (PMID 33513866, 2021). "A xenograft model of DPP-4-overexpressed epithelial ovarian cancer cells exhibited as larger bodies, but at the same time, displayed more chemosensitivity to paclitaxel." (PMID 34063285, 2021). "The role of the immune system in the development and progression of ovarian cancer is well established, and overexpression of the enzyme DPP4 has been noted in several cancer types) including ovarian cancer." (PMID 33513866, 2021). "It was also reported that DPP-4 expression and its secreted activity are uncoupled under hypoxia in ovarian cancer cells via the shedding of inactive DPP-4 from ovarian cancer cells." (PMID 34063285, 2021). "Overall, our findings provide proof of principle evidence for the repurposing of DPP4 inhibitors as a novel ovarian cancer immunotherapy." (PMID 33513866, 2021). "Whilst DPP4 over-expression in ovarian cancer tissues is well established, both pro- and anti-tumour effects have been attributed to DPP4 and in vitro analyses have generated significant conflict surrounding its functional significance." (PMID 33143089, 2020). "When cultured under conditions of low atmospheric oxygen for prolonged periods, we identified a significant and sustained increase in DPP4 expression in all ovarian cancer cell lines examined." (PMID 33143089, 2020). "In this study, the sitagliptin alone or in combination with paclitaxel was used to assess the influence of the DPP-4 inhibitor on ovarian cancer cells." (PMID 33256016, 2020). "This is the first report of uncoupled DPP4 expression and activity in ovarian cancer cells, and suggests a previously unrecognized, cell- and tissue-type-dependent mechanism for the regulation of DPP4 in solid tumours." (PMID 33143089, 2020). "Our data evidences a previously undescribed mechanism of DPP4 regulation in ovarian cancer cells mediated according to oxygen status, either directly via HIF-1α modulation or indirectly via its downstream targets." (PMID 33143089, 2020). "In this study we have investigated the role of hypoxic conditions on DPP4 expression and function in ovarian cancer cells in vitro." (PMID 33143089, 2020). "In this study, we provide the first evidence that DPP4 expression and enzyme activity are uncoupled under hypoxic conditions in ovarian cancer cells." (PMID 33143089, 2020). "We provide evidence for the hypoxic regulation of DPP4 in ovarian cancer cells and identify a potential matrix metalloproteinase-mediated mechanism of DPP4 proteolysis from the cell surface." (PMID 33143089, 2020). "Together these results show DPP4 mRNA expression is consistently upregulated under conditions of chronic hypoxic growth in ovarian cancer cell lines." (PMID 33143089, 2020).